GRK2 (G protein-coupled receptor kinase 2)
Diseases named in the same sentence as GRK2 in open-access papers (continued):
Sharing a sentence is not in itself a finding about the gene and the disease.
chronic heart failure (8 papers, 2009 to 2025). "Chronic heart failure is characterized by a severe impairment in myocardial β-adrenergic receptor (β-AR) signaling, which is caused by G protein-coupled receptor kinase-2 (GRK2)-mediated phosphorylation of β-AR." (PMID 40832145, 2025). "These processes are initiated by receptor phosphorylation, carried out by a family of serine/threonine kinases known as G protein-coupled receptor kinases (GRKs), with GRK2 being implicated in the gradual depletion of the cardiac inotropic reserves in chronic heart failure." (PMID 39062858, 2024). "GRK2 has been well characterized in the heart, where the onset of congestive heart failure (CHF) is associated with characteristic changes in myocardial expression of GRK2 and is known to significantly contribute to myocardial regulation and function in the failing heart." (PMID 20204079, 2009). "In the case of chronic heart failure, the high levels of catecholamines from the autonomic nervous system stimulating β1-ARs induce an increase in the expression of GRK2 within cardiomyocytes." (PMID 39062858, 2024). "This makes both β-adrenergic receptors as well as GRK2/5 therapeutical targets during chronic heart failure." (PMID 29367572, 2016). "In chronic heart failure, the adrenal chromaffin cell results in increased GRK2 levels, which in turn results in increased phosphorylation and desensitization of alpha2ARs and subsequent increased catecholamine secretion and, thus, circulating catecholamines." (PMID 20204079, 2009). "Chronic heart failure leads to upregulation of GRK2, both in cardiac myocytes and in adrenal chromaffin cells, which results in increased phosphorylation and desensitization of betaARs." (PMID 20204079, 2009). "Additionally, GRK2 is selectively upregulated in the adrenal gland (and in sympathetic neurons) in chronic heart failure, a disease characterized by both sympathetic nervous system hyperactivity and hyperaldosteronism." (PMID 31963151, 2020). "Based on our present findings, adrenal GRK2 upregulation could also very well lead to the elevated circulating aldosterone levels that are likewise known to accompany and complicate human chronic heart failure." (PMID 31963151, 2020). "This means that adrenal GRK2 upregulation could very well be the molecular culprit behind the increases in the circulating levels of both catecholamines and aldosterone in human chronic heart failure." (PMID 31963151, 2020). "Simultaneous inhibition of GRK2 in the heart, the adrenal gland, and brain with an appropriate pharmacological inhibitor may have a positive use in treating chronic heart failure and perhaps AD." (PMID 20204079, 2009).
depression (8 papers, 2013 to 2025). "Treatment with the GRK2 inhibitor paroxetine significantly improves depression scores, HRV, and LVEF, with greater improvements in cardiac function compared with fluoxetine." (PMID 41301929, 2025). "In patients with MI comorbid with depression, GRK2 expression in peripheral lymphocytes is inversely correlated with HRV and positively correlated with depression scores." (PMID 41301929, 2025). "PAR is a selective serotonin reuptake inhibitor used to treat depression and has been identified as a GRK2 inhibitor." (PMID 38037039, 2023). "Paroxetine (PRXT) serves as a selective GRK2 inhibitor which is widely used to treat anxiety and depression for several decades." (PMID 37815883, 2023). "Paroxetine is a GRK2 inhibitor that has been widely used to treat depression and anxiety over the last few decades." (PMID 35155607, 2021). "Therefore, further research is required to elucidate the mechanisms by which GRK2 contributes to ANS dysfunction and MI-associated depression." (PMID 41301929, 2025). "Cetirizine, a histamine H1 receptor antagonist currently used to relieve allergies, and paroxetine, a serotonin reuptake transport inhibitor and GRK2 inhibitor prescribed for depression, were further evaluated for their capacity to reduce JCPyV infection in primary cells." (PMID 39459893, 2024). "This agent used for clinical depression probably is not viable for use as a specific GRK2 inhibitor but is a great starting point for chemistry to develop novel GRK2 inhibitors that can be used eventually for cardiovascular disorders." (PMID 24133451, 2013). "GRK2 may represent a key protein linking ANS dysfunction, MI, and depression." (PMID 41301929, 2025).
rheumatoid arthritis (8 papers, 2013 to 2025). A chronic, systemic autoimmune disorder characterized by inflammation in the synovial membranes and articular surfaces. "Further, certain inflammatory conditions, including rheumatoid arthritis and multiple sclerosis, are associated with downregulation of GRK2 in lymphocytes." (PMID 33546162, 2021). "G protein-coupled receptor kinase 2(GRK2) down-regulation in leukocytes has been closely linked to the progression of chronic inflammatory disorders such as rheumatoid arthritis and multiple sclerosis." (PMID 24735118, 2014). "Notably, GRK2 is implicated in a range of autoimmune disorders, including rheumatoid arthritis (RA), inflammatory bowel disease (IBD), multiple sclerosis (MS), Sjögren's syndrome (SS), autoimmune myocarditis, hepatitis, and Graves' disease." (PMID 40224487, 2025). "It has been reported that patients with inflammatory autoimmune diseases, such as rheumatoid arthritis or multiple sclerosis, demonstrate a significant decrease in GRK2 level in their PBMCs as compared to healthy controls." (PMID 33546162, 2021). "Two prominent examples of inflammatory conditions in which GRK2 levels are seen to undergo downregulation include multiple sclerosis (MS) and rheumatoid arthritis (RA)." (PMID 33546162, 2021). "Clinically, in peripheral blood mononuclear cells of patients with active MS or with secondary progressive MS, as well as in lymphocytes of patients with rheumatoid arthritis (RA), GRK2 level were shown to be reduced." (PMID 29922165, 2018). "Since the production of proinflammatory cytokines is increased in rheumatoid arthritis (RA), it has been proposed that the increase in cytokines including IFN-γ and IL-6 could drive the observed decrease in GRK2 expression and activity in MNLs isolated from RA patients." (PMID 33546162, 2021).
gastric cancer (7 papers, 2018 to 2024). A primary or metastatic malignant neoplasm involving the stomach. "The non-coding RNA UCA1 plays a regulatory role in the stability of GRK2 protein in gastric cancer (GC) cells." (PMID 39130630, 2024). "The lncRNA UCA1 increases the ability of gastric cancer cells to metastasize by regulating the stability of GRK2 protein via the promotion of Cbl-c-mediated ubiquitination and degradation of GRK2, adding another level of complexity to the regulation of the expression of this kinase." (PMID 31432234, 2019). "In addition, UCA1 was shown to stimulate the ERK-MMP9 signaling in gastric cancer cells by interacting with G protein-coupled receptor kinase 2 (GRK2), stimulating its ubiquitination and degradation." (PMID 30441811, 2018).
portal hypertension (6 papers, 2009 to 2023). Increased blood pressure in the portal venous system. "GRK2 interacts with Akt and inhibits endothelial NO synthase activity and NO production, resulting in less severe portal hypertension in GRK2-deficient mice after liver injury." (PMID 24597858, 2014). "It has also been reported that an interaction between GRK2 and Akt inhibits the kinase activity of Akt in sinusoidal endothelial cells from portal hypertensive rats." (PMID 20204079, 2009). "It has been reported that GRK2 interacts with AKT and inhibits its activation to regulate endothelial cell nitric oxide synthase function in portal hypertension." (PMID 26402907, 2015). "GRK2 plays a key role in the regulation of a variety of these receptors and cardiac muscle expression is altered in pathological situations at the promoter level such as in CHF, portal hypertension, and other tissues and cells, such as lymphocytes in these conditions." (PMID 20204079, 2009).
autoimmune disease (4 papers, 2022 to 2025). A disorder resulting from loss of function or tissue destruction of an organ or multiple organs, arising from humoral or cellular immune responses of the individual to their own tissue constituents. "Dysregulation of GRK2 has been implicated in the etiology of several autoimmune disorders, including RA, IBD, and MS, where it disrupts immune homeostasis and promotes pathological inflammation." (PMID 40224487, 2025). "This review aims to elucidate the multifaceted role of GRK2 in immune function, autoimmune diseases, and cancer to uncover the remaining complexities associated with this kinase." (PMID 40224487, 2025). "GRK2 dysfunction is associated with cancer and autoimmune diseases, making it a potential therapeutic target." (PMID 40224487, 2025). "Dysregulation of GRK2 levels has been implicated in the pathology of autoimmune diseases and cancer, suggesting that it plays a significant role in immune tolerance, inflammation, and the immune system's ability to combat malignancy." (PMID 40224487, 2025). "The figure highlights GRK2′s critical involvement in immune modulation and its potential as a therapeutic target in autoimmune diseases." (PMID 40224487, 2025). "In summary, this review elucidates the pivotal role of GRK2 in the pathophysiology of autoimmune diseases and malignancies." (PMID 40224487, 2025). "This review aims to examine the biological processes involved in GRK2 in autoimmune diseases and identify a novel therapeutic target for treating autoimmune diseases." (PMID 40224487, 2025). "Comprehensive investigations into the biological and pathological functions of GRK2 have facilitated the development of therapeutic strategies aimed at targeting the GRK2 signaling pathway in cancer, inflammation, and autoimmune diseases." (PMID 40224487, 2025). "Activation or upregulation of GRK2 has been detected in many chronic diseases, including autoimmune diseases, cardiovascular diseases and metabolic diseases." (PMID 38037039, 2023). "Using targeted knockout and heterozygous mice, GRK2 has been shown to play an important role in atherosclerosis and other heart diseases, lymphocyte chemotaxis, and autoimmune diseases." (PMID 35430346, 2022). "The intracellular delivery of GRK2-specific peptide substrates may provide new opportunities for basic research into GRK2 and its biological roles in diagnosing and treating GRK2-related diseases, such as cancer and autoimmune disorders." (PMID 40224487, 2025). "This discussion primarily focuses on regulating GRK2 in autoimmune diseases and cancer." (PMID 40224487, 2025). "Overall, further detailing GRK2 and β-arrestin mechanism of action are warranted to better understand this signaling pathway and to evaluate the pharmacological potential of targeting these proteins in the treatment of acute inflammatory responses, autoimmune diseases, and pain." (PMID 35430346, 2022). "Based on above results and given that the GRK2/PI3K-AKT pathway contributes to the regulation of immune cell metabolism, we speculated that inhibiting the over activated PI3K-AKT pathway in immune cells might be effective methods for the treatment of RA and other autoimmune diseases such as AIH." (PMID 36188529, 2022).
colitis (4 papers, 2016 to 2025). Inflammation of the colon. "In a mouse model of DSS-induced colitis, it has been shown that GRK2 is involved in inflammatory gene transcription in DSS-treated mice." (PMID 40224487, 2025). "Then, we generated GRK2 heterozygous mice (GRK+/−) to explore the role of GRK2 in experimental colitis." (PMID 37242446, 2023). "We investigated the impact of GRK2 knockout on the EP4-cAMP-pCREB pathway in the DSS-induced colitis model, and the level of cAMP was found to decrease significantly in the GRK2+/+-DSS group." (PMID 37242446, 2023). "In this study, we investigated the role of GRK2 in macrophage polarization in UC, using biopsies from patients, a GRK2 heterozygous mouse model with dextran sulfate sodium (DSS)-induced colitis, and THP-1 cells." (PMID 37242446, 2023). "In order to investigate the role of GRK2 in the progression of colitis, we selected GRK2+/− heterozygous and WT littermates." (PMID 37242446, 2023). "In a model of dextran sodium sulfate (DSS)–induced colitis in GRK2 heterozygous mice, we found that prostaglandin E2 (PGE2) stimulation in the lamina propria of the colon could supersensitize EP4 receptors on monocytes." (PMID 40224487, 2025). "To confirm whether paroxetine affected GRK2 translocation in mice with DSS-induced colitis, we first detected the expression of GRK2/EP4/cAMP/pCREB in the mice’s LPMCs." (PMID 37242446, 2023). "Taken together, the current results show that GRK2 may act as a novel therapeutic target in UC by regulating macrophage polarization, and paroxetine as a GRK2 inhibitor may have therapeutic effect on mice with DSS-induced colitis." (PMID 37242446, 2023). "In response to the DSS challenge, heterozygous knockdown of GRK2 or myeloid-specific depletion of GRK2 significantly reduced the severity of IBD and colitis." (PMID 40224487, 2025). "Using DSS-induced colitis mice and the THP-1 cell line, we demonstrated that GRK2 is involved in the polarization of macrophages and provided evidence for the new mechanism of paroxetine in the treatment of UC." (PMID 37242446, 2023).
diabetic cardiomyopathy (4 papers, 2011 to 2022). Diabetic cardiomyopathy is a disorder of the heart muscle in people with diabetes. "The inhibition of GRK2 rescued AKT activity to promote Treg differentiation in mice with diabetic cardiomyopathy." (PMID 36188529, 2022). "In this study, we evaluated the myocardial and PBMCs GRK2 levels in early diabetic cardiomyopathy (DCM)." (PMID 31680450, 2020). "First, our present study revealed that GRK2 expression increased in both mice myocardium tissue and patient PBMCs with early diabetic cardiomyopathy." (PMID 31680450, 2020). "In the heart, at the same time, the GRK2 inhibitor ameliorated inflammatory and cytokine responses, reduced oxidative stress, and corrected patterns of fetal gene expression, typical of diabetic cardiomyopathy." (PMID 30934608, 2019). "The aim of this study is to produce the proof of concept in vitro and in vivo that GRK2 inhibition through KRX-C7 represents an effective therapeutic approach for the treatment of T2DM with positive effects on diabetic cardiomyopathy." (PMID 30934608, 2019). "The purpose of this study was to examine the expression levels of macrophage migration inhibitory factor (MIF) and G protein-coupled receptor kinase 2 (GRK2) in patients with early diabetic cardiomyopathy, and to investigate the mechanisms involved in MIF expression and GRK2 activation." (PMID 21283592, 2011).
Glucose intolerance (4 papers, 2017 to 2025). Glucose intolerance (GI) can be defined as dysglycemia that comprises both prediabetes and diabetes. "We have shown that the embryonic loss of GRK2 in the entire pancreas leads to glucose intolerance, increased body weight, and reduction in cardiac function." (PMID 40054692, 2025). "Pancreatic deletion of GRK2 in mice resulted in glucose intolerance with diminished insulin secretion." (PMID 34045505, 2021). "Decreased GRK2 levels in global GRK2+/− mice prevent the development of an insulin resistant and obese phenotype in terms of body weight gain, glucose intolerance, and insulin insensitivity in skeletal muscle and liver, thus maintaining glucose homeostasis and favoring energy expenditure." (PMID 31752326, 2019). "Control siRNA-transfected ob/ob mice showed greater glucose intolerance than the control siRNA-transfected lean mice, and the GRK2 siRNA-transfected ob/ob mice showed an improvement in glucose clearance from that in the control siRNA-transfected ob/ob mice, as shown by the GTTs." (PMID 28814745, 2017).
Hepatic steatosis (4 papers, 2019 to 2026). Steatosis is a term used to denote lipid accumulation within hepatocytes. "Our findings suggest that GRK5-IN-2 attenuates hepatic steatosis by suppressing triglyceride synthesis and promoting mitochondrial fatty acid oxidation, potentially through inhibition of GRK2 alongside GRK5." (PMID 40666930, 2025).
Hyperglycemia (4 papers, 2017 to 2026). An increased concentration of glucose in the blood. "In brief, upregulation of GRK2 is involved in D1R desensitization induced by oxidative stress or insulin treatment in patients with hyperglycemia." (PMID 39438268, 2024). "In this context, we recently reported that a reduction of GRK2 levels in myeloid cells prevents the development of glucose intolerance and hyperglycemia after a high fat diet (HFD) by downregulating a pro-inflammatory macrophage profile." (PMID 33020373, 2020). "Thus, it is tempting to suggest that the hyperinsulinemia and hyperglycemia associated with insulin-resistant conditions, and clinically associated with T2DM, trigger the observed upregulation of GRK2 levels and activities under such conditions." (PMID 28814745, 2017).
Myocardial fibrosis (4 papers, 2020 to 2023). "This increased expression was associated with increased NF-ĸB(p65) and decreased IĸBα expression, suggesting that GRK2 can cause myocardial fibrosis by activating the NF-ĸB signaling pathway." (PMID 38139099, 2023). "Recently, anomalous GRK2 level and activity have been observed in various tissues during fibrosis pathophysiology such as hepatic fibrosis, myocardial fibrosis, pulmonary fibrosis, etc." (PMID 35111168, 2021). "Accordingly, other studies show that the up-regulated expression of p-GRK2 consisted with the activation of the ERK1/2/Smad2/3 signaling pathway is conducive to the production of collagen I/III in myocardial fibrosis mice." (PMID 35111168, 2021). "The results of this study suggest that the low expression level of GRK2 could inhibit myocardial fibrosis." (PMID 35111168, 2021). "Taken together, GPCRs-mediated signaling, specifically β2AR, GRK2, and GRK5, is the critical positive regulator of myocardial fibrosis, therefore representing a novel therapeutic target for the limitation of excessive myofibroblast activation and interstitial fibrosis in the diseased heart." (PMID 34572061, 2021).